IL2 (interleukin 2)
Diseases named in the same sentence as IL2 in open-access papers (continued):
Sharing a sentence is not in itself a finding about the gene and the disease.
type 1 diabetes (continued). "Several phase 1/2 clinical trials showed that low-dose interleukin-2 (IL-2) treatment is a safe and effective strategy for the treatment of chronic graft-versus-host disease, hepatitis C virus-induced vasculitis, and type 1 diabetes." (PMID 32308767, 2020). "To date, clinical research with radiolabelled IL-2 (e.g. 99mTc-HYNIC-IL-2) has been performed in various inflammatory diseases in over 1000 patients (inflammatory bowel disease, atherosclerosis, thyroiditis, diabetes type 1, etc.)." (PMID 31076906, 2019). "Complexing of F5111.2 with human IL-2 led to the remission of type 1 diabetes and reduced disease severity in mouse models of graft-vs.-host disease and experimental autoimmune encephalomyelitis." (PMID 30930900, 2019). "Imbalance between T reg cells and T effector cells in the pancreatic islet has been implicated in breakdown of self-tolerance and development of type 1 diabetes in a mouse model; IL-2 administration is protective in this model by promoting T reg survival." (PMID 30952858, 2019). "Although the potential toxicity of IL-2 treatment in patients with type 1 diabetes has been reported, we note very high doses of Proleukin were used which were accompanied by a large induction of NK cells and eosinophils." (PMID 30446251, 2018). "On day −4, their splenocytes were harvested and incubated with PLP139 and IL-2 for 72 h, a protocol that has been shown to expand Tregs in vitro and used in clinical protocols for Treg immunotherapy of organ transplant and type 1 diabetes." (PMID 29552007, 2018). "One study, limited to specific SNPs in regions associated with type 1 diabetes, identified that the MHC, IL-2 (IL2) and renalase (RNLS) gene regions showed evidence of association with AAD." (PMID 28983737, 2018). "An example highlighting the heterogeneity seen within type 1 diabetes cohorts demonstrated variation in the IL-2 sensitivity of Tregs from different individuals." (PMID 28770318, 2017). "A Phase I/II clinical trial in type 1 diabetes demonstrated the safety of low-dose IL-2 administration and an increase in the frequency of pTregs was observed." (PMID 28770318, 2017). "In the present study, we observed that STZ-type 1 diabetes in rats induced a significant increase of plasmatic levels of IL-2 and IFN-γ (Th1 cytokines) and a decrease of IL-4 (Th2 cytokine) and IL-10 (regulatory cytokine) concentrations." (PMID 29317893, 2017). "Frank Waldron-Lynch and colleagues investigate immune cell biomarker responses in patients with type 1 diabetes following a single dose of recombinant interleukin-2." (PMID 27727279, 2016). "Several clinical studies in HCV-induced vasculitis, GvHD, and type 1 diabetes have reported that low dose IL-2 therapy is safe, expands Treg frequency, and improves their functional capacity." (PMID 27446862, 2016). "As a consequence, the demonstration of increased IL-21 production in type 1 diabetes patients supports the findings from genetic studies of type 1 diabetes implicating a dysfunction of the IL-2 signalling pathway in the pathogenesis of the disease." (PMID 25652388, 2015). "Nevertheless, it is already known that, like CD4+ Tregs, CD8+ Tregs expand in response to IL-2 treatment, as we previously showed in a clinical trial using low-dose IL-2 in hepatitis C virus-induced vasculitis and type 1 diabetes." (PMID 25926835, 2015). "The study by the group of David Klatzmann highlights the effects of IL-2 in modulating T cell responses in type 1 diabetes." (PMID 26029214, 2015). "The aim of this study was to analyse the performance of three recruitment sources and the effect of publicity events during the Adaptive study of IL-2 dose on regulatory T cells in type 1 diabetes (DILT1D)." (PMID 25881192, 2015). "RNF128 encodes a type I transmembrane protein located in the endocytic pathway and its expression significantly inhibited activation-induced IL4 and IL2 that are involved in type I diabetes mellitus pathway (KEGG: hsa04940)." (PMID 24344781, 2013).
type 1 diabetes (continued). "We further discuss a potential link between the immunomodulatory role of interleukin-2 and the pathogenesis of type 1 diabetes." (PMID 21647403, 2011). "With increasing research on the immune regulatory mechanism of low-dose IL-2, IL-2 has gained attention as a potential treatment for various immunological diseases, such as graft-versus-host disease (GvHD), hepatitis C–related vasculitis, and type 1 diabetes." (PMID 38807592, 2024). "In a study conducted by D’Addio and co-authors, it was shown that the SARS-CoV-2 mRNA vaccine may lead to a reduced cellular immune response specific to SARS-CoV-2, particularly in relation to IL2, in individuals with type 1 diabetes." (PMID 39625479, 2024). "However, e.g. islet-specific antigen therapy alone has been disappointing in trials with type 1 diabetes patients and it has been suggested that antigen therapy must be combined with a Treg-inducing agent such as low-dose IL-2." (PMID 37741949, 2023). "In addition to IL-2, autologous transfer of in-vitro expanded naïve Tregs from human plasma has demonstrated in-vivo stability and safety in type 1 diabetes and graft versus host disease patients." (PMID 38983511, 2022). "With the recent report that FMT from healthy donors halts the progression of new-onset type 1 diabetes in humans, our results suggest that the use of IL-2–tuned FMT or of FMT enriched in specific taxa could represent an improved treatment modality." (PMID 35917175, 2022). "Interestingly, MAIT cell IL-17 production positively correlated with MAIT cell TNF-α production in healthy donors and also with other Th1 cytokine production (IFN-γ and IL-2) in individuals with long-term type 1 diabetes." (PMID 34350463, 2021). "Additionally, we assessed the concentrations of IFN-γ, IL-2, IL-4 and IL-10 in the plasma of individuals with type 1 diabetes and healthy group." (PMID 34830017, 2021). "It has been shown in non-obese diabetic mice that neutralizing anti-IL-2 antibodies accelerate type 1 diabetes and that a reduction in IL-2 could impact Treg function and thus immune tolerance." (PMID 35008717, 2021). "Furthermore, the cytokine secretion profile during the development of type 1 diabetes is typical of a Th1 pattern immune response, with the inflammatory cytokines IL-2, TNF-α, and IFN-γ being secreted in high quantities." (PMID 30254638, 2018). "In addition, it is also clear that autoimmune diabetes (type I diabetes) requires IL-2 for the stable maintenance of Treg cells." (PMID 29389956, 2018). "For example, low-dose IL-2 therapies for type 1 diabetes selectively expanded existing Treg populations which could suppress islet cell destruction." (PMID 29312311, 2017). "Here, in the Adaptive Study of IL-2 Dose on Regulatory T Cells in Type 1 Diabetes (DILT1D), the effects of single-dose aldesleukin were investigated by observing multiple biomarkers before treatment (baseline), at 90 min after drug administration, daily for 4 d, and then intermittently for 9 wk." (PMID 27727279, 2016). "For example, delivery of IL-2/anti-IL-2-antibody complexes in pre-clinical studies stimulates Treg expansion and reduces disease in models of type 1 diabetes (T1D), experimentally induced autoimmune encephalomyelitis (EAE), collagen-induced arthritis, and angiotensin II-induced aortic stiffening." (PMID 25741338, 2015). "Seven patients with type 1 diabetes received 3 MIU of IL-2/day for 5 days." (PMID 25926835, 2015). "Previously, we showed that variants in IL2RA that predispose to type 1 diabetes reduce the level of IL-2RA/CD25 on Tregs and memory Teff cells, thereby potentially increasing the amount of homeostatic IL-2 production required for Treg survival and function, and limiting Tfh differentiation." (PMID 25652388, 2015).
type 1 diabetes (continued). "Reports have indicated that polymorphisms in the genes encoding IL2 are associated with ulcerative colitis, inflammatory bowel disorder, rheumatoid arthritis and Behcet’s disease, whereas the receptor of IL2, the IL2R alpha variants were associated with type I diabetes and multiple sclerosis." (PMID 23217119, 2012). "Among the better known examples of this phenomenon is type 1 diabetes (T1D), in which a decrease in the sensitivity of Tregs for IL-2 precipitates the evasion of β cell–specific, diabetogenic T cells from Treg-mediated suppression." (PMID 39704171, 2024). "Alternatively, as IL-2 signalling increases the proliferation of the conventional T cells and Tregs alike, IL-2 signalling might not decrease the risk of type 1 diabetes only by increasing tolerance but also by promoting appropriate responses to pathogens." (PMID 39271518, 2024). "The combination of antigen (PPI) with the three immune response modifiers (TGFβ1, IL-10, and IL-2) is intended to induce antigen-specific Treg accumulating in the pancreas, and to preserve beta cell function in type 1 diabetes (T1D)." (PMID 37741949, 2023). "Another cytokine that may participate in the pathogenesis of type 1 diabetes in children is IL-2." (PMID 34830017, 2021). "Low-dose IL-2 has been reported to selectively expand Treg and inhibit Th17 cells and so has a broad therapeutic potential in immune-mediated inflammatory diseases, including rheumatoid arthritis, systemic lupus erythematosus, psoriasis, Crohn’s disease, and type 1 diabetes." (PMID 34271972, 2021). "Our aim was to evaluate the association of the four IL2 polymorphisms (rs6822844, rs6534349, rs2069762 and rs3136534) with type 1 diabetes (T1D) in the Polish population, and to correlate them with the serum interleukin-2 levels." (PMID 24154763, 2013). "In addition, in the non-obese mouse model of type 1 diabetes, allelic variation of IL-2 was associated with reduced IL-2 expression correlating with impaired Treg activity." (PMID 19956753, 2009). "For instance, in type 1 diabetes, the upregulation of IL-12/IL-18 allows NK cells to enhance CD25 expression, directly competing with Tregs for IL-2, which reduces Treg suppression capability." (PMID 39290699, 2024). "Our findings support the targeting of IL-2, IL-6 and TYK2 signalling in prevention of type 1 diabetes." (PMID 39271518, 2024). "Utilizing low-dose IL-2 administration, promising results have been demonstrated in clinical trials of patients with hepatitis C virus-induced vasculitis, GvHD, as well as Type 1 diabetes (T1D)." (PMID 36562079, 2023). "Our study demonstrates a reduction of circulatory IL-2 in pSS patients and accompanied with enhanced Th17 generation, which is consistent with previous reports that reduced IL-2 availability in SLE and type I diabetes patients." (PMID 30150979, 2018). "Subsequently, the beneficial effect of low-dose IL-2 therapy was also observed in GVHD, alopecia areata, type 1 diabetes (T1D), and systemic lupus erythematosus." (PMID 29163527, 2017). "The authors notably report how injection of low doses of IL-2 modulates the levels of CD8+ Tregs in vivo, in both mice and in patients with type 1 diabetes, following their numbers and phenotype." (PMID 26029214, 2015). "Three phase I/II trials have evaluated the effects of IL-2 in chronic GVH, type 1 diabetes and HCV related infectious cryoglobulinemic vasculitis." (PMID 26629828, 2015). "Thus, natural history studies and clinical prevention trials should pinpoint the optimal stage of pathogenesis at which to interfere with IL-2, IL-6 or TYK2 signalling to prevent type 1 diabetes." (PMID 39271518, 2024). "IL-2, as a pleiotropic cytokine indispensable to proper T reg cell function, was reported as a non-pancreatic autoimmune target in type 1 diabetes (T1D)." (PMID 35563556, 2022). "Literature data also shows that IL-2 reverses established type 1 diabetes in non-obese diabetic mice by a local effect on pancreatic regulatory T cells." (PMID 35596173, 2022).
type 1 diabetes (continued). "In adults with long-term type 1 diabetes, MAIT cells displayed an activated and exhausted phenotype characterised by high CD25 and programmed cell death 1 (PD1) expression and a decreased production of proinflammatory cytokines, IL-2, IFN-γ and TNF-α." (PMID 34350463, 2021). "Treatment with low-dose IL-2 has shown promise in numerous inflammatory disorders including chronic graft vs.-host-disease (GVHD), allograft survival, systemic lupus erythematosus, and type I diabetes, among others." (PMID 30930900, 2019). "In support of this, a lower frequency of Tregs has been detected in the blood of young diabetic patients, and it has been described that Tregs from type 1 diabetes patients and NOD mice show functional deficits, possibly related to defects in the IL-2/IL-2Rα pathway." (PMID 28356069, 2017). "The Adaptive study of IL-2 dose frequency on Tregs in type 1 diabetes(DILfrequency) is a mechanistic, non-randomised, repeat dose open-label, response-adaptive study of 36 participants with T1D." (PMID 26646829, 2015). "While IL-2 was shown to significantly increase the proportion of circulating Treg cells in all studies, this cytokine was also shown to ameliorate skin involvement in GVHD as well as in vasculitis, but was inefficient in type 1 diabetes." (PMID 26629828, 2015). "Adaptive study of IL-2 dose on regulatory T cells in type 1 diabetes (DILT1D) is a single centre non-randomised, single dose, open label, adaptive dose-finding trial." (PMID 24898091, 2014). "Downregulated genes highlighted compared to T-ALL included: “autoimmune thyroid disease”, “allograft rejection”, “graft versus host disease”, and “type I diabetes mellitus” all at (p≤0e0), together with “JAK-STAT signalling” (p≤3.3e16); and “upregulated by IL-2 in CTCL” (p≤3.0e15)." (PMID 23372669, 2013). "Short-term low-dose IL-2 treatment preferentially targets Tregs rather than Teff cells and induces a long-term protection in experimental type 1 diabetes." (PMID 22450711, 2012). "Similarly, transcripts of candidate genes for type 2 diabetes (Blk, C2cd4a, C2cd4b, Cdkn2a, Hnf1a, Mtnr1b, Pou5f1, Slc30a8) and type 1 diabetes (Cd69, Il2, IL27) were not expressed in the brain." (PMID 39920851, 2025). "Moreover, in type 1 diabetes mice, when Treg cells are depleted, the level of IL-2 increases, but CD4 + T cells that secrete IL-2 do not increase." (PMID 37391717, 2023). "By inducing immune tolerance, Ld-IL2 therapy is emerging as a new approach to treat autoimmune and inflammatory diseases and has shown safety and promising efficacy in a broad range of conditions including GVHD, SLE, type 1 diabetes and hepatitis C virus (HCV) induced vasculitis." (PMID 34618873, 2021). "In addition, depletion of Treg cells led to an increase in IL-2 levels in mice with type 1 diabetes, but the numbers of CD4+ T cells that secreted IL-2 did not increase significantly." (PMID 33013198, 2020).
Sepsis (131 papers, 2004 to 2026). Sepsis is defined as life-threatening organ dysfunction caused by a dysregulated host response to infection. "After excluding sepsis and engraftment syndrome cases, the IL-2/IL-4 ratio on day +7 remained associated with aGVHD." (PMID 40718494, 2025). "Inflammatory factors such as AXIN-1, FGF-19, FGF-23, IL-4, and OSM were negatively causally associated with sepsis, while IL-2 was positively associated." (PMID 39205680, 2024). "In our study, we identified several inflammatory factors, including FGF-19, AXIN1, FGF-23, IL-4, OSM, and IL-2, that showed statistically significant associations with sepsis risk using the IVW method in MR analyses." (PMID 39205680, 2024). "Conversely, men predominantly display Th1 responses and overproduce TNF-α, IL-1β, IL-2, IL-6, and IL-8, which in turn is often associated with poor outcomes, such as septicaemia and bacteremia." (PMID 37004108, 2023). "These theoretical assumptions are supported by the results of clinical studies of recombinant IL-2 in patients with immunosuppressive status associated with systemic inflammatory response syndrome caused by sepsis or serious trauma." (PMID 32722596, 2020). "That said, CD8+ T cell exhaustion remains a hallmark of sepsis, as evidenced by the recently reported decrease in the synthesis of IL-2 and TNFα by CD8+ T cells." (PMID 33613540, 2020). "On the other hand, males present predominantly Th1 responses and overproduce tumor necrosis factor α (TNF-Uα), IL-1β, IL-2, IL-6, and IL-8, which in turn are frequently associated with inappropriate outcomes such as sepsis and bacteremia." (PMID 29925409, 2018). "Our results indicate that the occurrence of infection and sepsis are linked with deficient γc family cytokines gene expression, specifically IL-2 and IL-7." (PMID 21711552, 2011). "The onset of infection and subsequent occurrence of sepsis is linked with anomalous gene expression of γc cytokines IL-2 and IL-7." (PMID 21711552, 2011). "During the immunosuppressive phase of sepsis, a deficiency in IL-2 may worsen immune suppression and increase the risk of secondary infections." (PMID 40166075, 2025). "Similarly, its association with decreased IL-2 levels correlated with a reduced sepsis risk, contributing 12.565% to its protective effect." (PMID 39205680, 2024). "Similarly, 9-hydroxystearate’s association with increased FGF-19 and decreased IL-2 correlated with a reduced sepsis risk, contributing 9.436% and 12.565% respectively to the protective effect of 9-hydroxystearate." (PMID 39205680, 2024). "According to our results, when used in addition to routine blood tests, IL-6 and IL-2 can improve overall diagnostic ability in predicting BI, while IL-10 could increase specificity in early sepsis recognition." (PMID 35582414, 2022). "Patients with infection and sepsis have deficient IL-2 and IL-7 gene expression in PBLs." (PMID 21711552, 2011). "• The occurrence of infection and sepsis are linked with deficient IL-2 and IL-7 gene expression." (PMID 21711552, 2011). "Thus most of the early literature described alternative methods of managing these patients than those used for sepsis, as the desirable therapeutic effects were thought to be linked to the toxicity and the inciting factor (IL-2 administration) was within the physician's control." (PMID 31546315, 2014). "In the CLP-induced sepsis kidney injury model, the IL-2 gene exhibited low expression, whereas the CXCL8, IL-1β, TNF, IL-6, and IL-10 genes demonstrated high expression levels." (PMID 40166075, 2025). "IL-2 levels on days +14 and +21 were significantly elevated in patients with sepsis than those in the control group (P = 0.021 and P = 0.020)." (PMID 40718494, 2025). "A study by Liu (2010) examining dynamic changes in circulatory cytokine and chemokine levels during the early phase of sepsis also found a significant positive correlation between IL-1β and IL-2." (PMID 40283868, 2025).